KNOP1 (lysine rich nucleolar protein 1)
Synonyms: C16orf88; FAM191A; TSG118; 101F10.1
Tractability: PROTAC: UniProt records ubiquitination sites on it; ubiquitination databases record sites on it; its protein half-life has been measured.
Gene: Protein-coding gene on chromosome 16 (19,701,937 to 19,718,552, reverse strand). Ensembl gene ENSG00000103550.
Subcellular location: Nucleus, nucleolus
Subcellular location (Human Protein Atlas): Nucleoli; Nucleoli rim; Cytosol
Gene Ontology:
Molecular function: protein binding; RNA binding
Cellular component: nucleolus
Genetic constraint (gnomAD): Loss-of-function variants: 27 observed, 38.69 expected, observed/expected ratio (o/e) 0.7, 90% interval 0.51 to 0.96. The upper end of that interval is the gene's LOEUF score, 0.96, which puts it in group 4 of 6, group 1 being the genes least tolerant of losing a copy. Missense variants: 540 observed, 588.57 expected, observed/expected ratio (o/e) 0.92, 90% interval 0.85 to 0.99. Synonymous variants: 204 observed, 220.3 expected, observed/expected ratio (o/e) 0.93, 90% interval 0.82 to 1.04.
Homologues: Orthologues: chimpanzee KNOP1 (98% identical), macaque KNOP1 (91% identical), dog KNOP1 (75% identical), rabbit KNOP1 (71% identical), pig KNOP1 (71% identical), guinea pig KNOP1 (68% identical), rat Knop1 (65% identical), mouse Knop1 (65% identical), tropical clawed frog knop1 (33% identical), zebrafish knop1 (26% identical).
Diseases named in the same sentence as KNOP1 in open-access papers:
KNOP1 is named in the same sentence as 3 diseases in open-access papers, as found by Europe PMC text mining. Sharing a sentence is not in itself a finding about the gene and the disease. The quoted sentences say what the papers report.
Hepatic steatosis (1 paper, 2015). Steatosis is a term used to denote lipid accumulation within hepatocytes. "Furthermore, by integrating transcriptomic information for the liver and adipose tissue, we identified two high-confidence candidate genes (Gde1 and Knop1) for hepatic steatosis on chromosome 7." (PMID 26067236, 2015).
pancreatic cancer (1 paper, 2022). "Six genes, EARS2, ARL6IP1, DNAJA3, KNOP1, RPUSD1, and TMEM186, significantly coexpressed with PALB2 in both breast and pancreatic cancer." (PMID 35779338, 2022).
tumor (2 papers, 2023 to 2024). "The results of ANKRD52 level expressed that the HOXC10, KNOP1, and TRIM45 in the tumor tissue were higher in the paracancerous tissue, and the opposite was true for SGPP1." (PMID 37521466, 2023).